MPO (myeloperoxidase)
Diseases named in the same sentence as MPO in open-access papers (continued):
Sharing a sentence is not in itself a finding about the gene and the disease.
pulmonary fibrosis (continued). "Among the three types of AAV, MPA, which is strongly associated with myeloperoxidase ANCA (MPO-ANCA), is most frequently accompanied by pulmonary fibrosis (15–47% of cases)." (PMID 31675941, 2019). "In the real-world setting, nephrologists often consult with pulmonologists about the management of pulmonary fibrosis in patients with MPO-ANCA nephritis." (PMID 31675941, 2019). "Some excellent studies have addressed the clinical features, including the prognosis of pulmonary fibrosis, in patients with serum MPO-ANCA positivity." (PMID 31675941, 2019). "This study was performed to compare the prognosis of a usual interstitial pneumonia (UIP) pattern of lung fibrosis in patients with MPO-ANCA nephritis with the prognosis of idiopathic pulmonary fibrosis (IPF)." (PMID 31675941, 2019). "MPO-ANCAs have been reported in 7% to 33% of patients with interstitial pneumonia and idiopathic pulmonary fibrosis." (PMID 26266064, 2015). "In another study, corticosteroids and/or another immunosuppressive drug were given for most patients with MPO-ANCA-positive pulmonary fibrosis." (PMID 24468083, 2014). "Since then, several additional reports have described ANCA-, MPO-ANCA-, and MPA-associated pulmonary fibrosis." (PMID 24468083, 2014). "Research has indicated that oral administration of melatonin can substantially decrease nitrate/nitrite levels, lower MDA levels, and enhance myeloperoxidase (MPO) content, thereby alleviating pulmonary interstitial fibrosis in neonatal rats suffering from BPD and increasing alveolar counts." (PMID 40735644, 2025). "A growing body of evidence indicates that NETs and their individual components contribute significantly to the progression of pulmonary fibrosis, including the DNA core strands themselves, histones, components of neutrophil granules (e.g., MPO, NE), HMGB1, and others." (PMID 40001601, 2025). "Also, interstitial pulmonary fibrosis was determined on computerized tomography, and myeloperoxidase antineutrophil cytoplasmic autoantibody was positive." (PMID 37003978, 2023). "Mogroside IIIE has the greatest inhibitory activity on NO (an important inflammatory factor) release from LPS-induced RAW264.7 cells, eliminating pulmonary fibrosis and demonstrating a decrease in myeloperoxidase (MPO) activity, collagen deposition and pathology scores." (PMID 36235155, 2022). "Some recent studies showed that MPO-ANCA positivity was associated with subsequent MPA development in patients initially diagnosed as having IIPs, especially usual interstitial pneumonia/idiopathic pulmonary fibrosis (UIP/IPF)." (PMID 34732182, 2021). "In a cohort of 61 patients with idiopathic pulmonary fibrosis, 6 individuals became MPO-ANCA positive during follow-up, with a median duration of 23 months (range, 0 to 71 months); 2 patients developed crescentic GN and subsequently received a diagnosis of MPA." (PMID 33909191, 2021). "Pulmonary fibrosis increased the MPO activity, while adelmidrol administration reduced it." (PMID 32660140, 2020). "However, few studies have focused on the development of pulmonary fibrosis in patients with MPO-ANCA nephritis." (PMID 31675941, 2019). "However, during the comorbidity of A. suum infection with pulmonary fibrosis in mice, we found a more pronounced MPO and EPO activity in the lungs than in the case of A. suum infection or bleomycin-induced pulmonary fibrosis only." (PMID 31765381, 2019). "Previous studies have shown that NETs components such as NNA, MPO, NE, and histones release cytokines that lead to inflammation, epithelial mesenchymal transition, epithelial injury, FB activation, and FB myofibroblast transformation, all of which promote the progression of lung fibrosis." (PMID 41262541, 2025).
pulmonary fibrosis (continued). "Indeed, anti-MPO has shown a direct contribution to lung fibrosis in ANCA-ILD through oxidative stress and the release of proteolytic enzymes or neutrophil extracellular traps (NETs) that trigger fibroblast proliferation and the deposition of extracellular matrix in the lung tissue." (PMID 39797313, 2025). "Lung fibrosis is in particular associated with MPO-ANCA rather than PR3-ANCA." (PMID 37331172, 2023). "Thus, the present study, which is the first study to elucidate the prognosis of a UIP pattern of pulmonary fibrosis in patients with MPO-ANCA nephritis, may have clinical relevance." (PMID 31675941, 2019). "Furthermore, the excessive free radicals will result in oxidative stress or chronic inflammation, the related enzymes have a significant function in the processing of lung fibrosis, and thus, the activities of the oxidant enzymes (MPO and MDA) were also measured in this study." (PMID 28245556, 2017). "The pathologic mechanism of pulmonary fibrosis and positive MPO-ANCA remains unclear." (PMID 26266064, 2015). "In this regard, some data show an excess of premature AAV mortality related to respiratory disease in anti-MPO positive patients, particularly higher in MPA patients with pulmonary fibrosis." (PMID 39797313, 2025). "In pulmonary fibrosis models, it restores superoxide dismutase (SOD) activity, reduces MDA and myeloperoxidase (MPO) levels, and decreases pro-inflammatory cytokines (TNF-α, IL-6, endothelin-1)." (PMID 41154606, 2025). "Animal experiments showed that curcumin inhibited hydroxyproline content, collagen type I, TGF-β1 expression, myeloperoxidase (MPO), and superoxide generation in the lungs of amiodarone rats, thereby improving pulmonary fibrosis." (PMID 41357857, 2025). "In terms of laboratory, imaging, and biopsy criteria, 60 (36.6%) and 32 (19.5%) patients exhibited MPO-ANCA (or P-ANCA) positivity (+6) and pulmonary fibrosis or ILD (+3), respectively." (PMID 39407892, 2024). "The inflammatory activities of IL-1β, IL-6, MPO, TGF-β1, and TNF-α in the lung tissues of both normal control rats and BLM-induced lung fibrosis rat models were determined." (PMID 35268069, 2022). "In addition, MPO-ANCA per se may play a role in the pathogenesis of pulmonary fibrosis." (PMID 33909191, 2021). "Anti-neutrophil cytoplasmic antibodies (ANCA), mainly anti-myeloperoxidase (MPO) antibodies, have been frequently identified in patients with idiopathic pulmonary fibrosis (IPF)." (PMID 34207641, 2021). "Another study showed that 100 mg/kg of saffron reduced MDA, Myeloperoxidase, and tumor-necrosis factor-alpha (TNF-α) in pulmonary fibrosis." (PMID 34195027, 2021). "In the 1990s, studies in hamster models of fibrosis indicated that PFD ameliorates bleomycin-induced lung fibrosis by suppressing oxidative stress mediators, such as MDA and MPO, and enhancing SOD activity." (PMID 35126133, 2021). "We retrospectively reviewed the medical records of 126 patients with MPO-ANCA nephritis and identified 31 with a UIP pattern of lung fibrosis on high-resolution or thin-slice computed tomography (CT)." (PMID 31675941, 2019). "In vivo experiments showed that BLM combined with SCU in the treatment of mice bearing H22 ascites tumor prolonged the survival time, alleviated BLM-induced pulmonary fibrosis, reduced the production of TNF-α; IL-6, and the levels of MDA and MPO." (PMID 29962947, 2018). "However, whether MPO positivity is a predisposing factor for pulmonary fibrosis in MPA patients is not yet understood." (PMID 24468083, 2014). "All were positive for myeloperoxidase-anti-neutrophil cytoplasmic antibody (ANCA), with 6 patients being positive at the time of their initial diagnosis of pulmonary fibrosis." (PMID 24468083, 2014). "In addition, Thal has been reported to reduce MPO, NO, MDA and ROS and to enhance the activity of SOD and thioredoxin reductase in bleomycin- or paraquat-induced pulmonary fibrosis murine models." (PMID 35126133, 2021).
pulmonary fibrosis (continued). "Our series also included 2 MPO-ANCA-positive patients with pulmonary fibrosis but no other manifestations of systemic vasculitis." (PMID 32977717, 2020). "Evidence indicates that NETs components such as DNA, myeloperoxidase (MPO), neutrophil elastase (NE) and histones release cytokines that lead to inflammation, epithelial-mesenchymal transformation (EMT) or epithelial damage, all of which promote the progression of lung fibrosis." (PMID 36658568, 2023). "However, the clinical features of pulmonary fibrosis in patients with MPO-ANCA nephritis have not been well documented." (PMID 31675941, 2019). "Furthermore, all 19 patients (100%) were myeloperoxidase (MPO)-ANCA-positive (range, 43 – > 200 EU; healthy normal control values are < 10 EU as measured by ELISA), with 6 patients (31.6%) being ANCA-positive at the time of diagnosis of pulmonary fibrosis." (PMID 24468083, 2014). "The highly specific, high-titer MPO-ANCA (>134 U/mL), the presence of incipient pulmonary fibrosis on imaging, negative microbiological cultures, and the absence of clinical response to appropriate antibiotics collectively reinforced an autoimmune process." (PMID 41515620, 2026). "Corroborating our previous observations, we found increased MPO and EPO activity in A. suum infected mice but not in bleomycin-induced pulmonary fibrosis." (PMID 31765381, 2019). "Our patient developed progressive interstitial pneumonitis and pulmonary fibrosis that was first diagnosed approximately one month after the development of ITP and occurred in spite of the administration of high dose steroids for ITP and initially without increase in MPO-ANCA and other signs of MPA." (PMID 26266064, 2015).
eosinophilic granulomatosis with polyangiitis (49 papers, 2014 to 2025). Eosinophilic granulomatosis with polyangiitis (EGPA), previously known as Churg-Strauss syndrome, is a systemic vasculitis of small-to medium vessels, characterized by asthma, transient pulmonary infiltrates, and hypereosinophilia. "The chronic airway inflammation in severe eosinophilic asthma (SEA) suggests potential autoimmune aetiology with unidentified autoantibodies analogous to myeloperoxidase (MPO) in ANCA-positive EGPA (eosinophilic granulomatosis with polyangiitis)." (PMID 37334358, 2023). "The aim of this study is to investigate the clinical significance of myeloperoxidase (MPO)–antineutrophil cytoplasmic antibody (ANCA) on eosinophilic granulomatosis with polyangiitis (EGPA) from a longitudinal Chinese cohort." (PMID 35833130, 2022). "A case of eosinophilic granulomatosis with polyangiitis (EGPA) in which chronic rhinosinusitis (CRS) was improved with a reduction in the myeloperoxidase-antineutrophil cytoplasmic antibody (MPO-ANCA) titer after the addition of mepolizumab is reported." (PMID 33859858, 2021). "Previous history of worsening asthma, nasal polyps, elevated eosinophil count and positive ANCA with a specific anti-MPO antibody is consistent with eosinophilic granulomatosis with polyangiitis (EGPA)." (PMID 26699763, 2016). "Positive P-ANCA and MPO-ANCA further supported the diagnosis of eosinophilic granulomatosis with polyangiitis (EGPA)." (PMID 40718113, 2025). "MPO‐ANCA is elevated in conditions such as microscopic polyangiitis, allergic granulomatosis and angiitis (Churg‐Strauss syndrome), pauci‐immune necrotizing crescentic glomerulonephritis, systemic sclerosis, and Goodpasture syndrome." (PMID 40642133, 2025). "EGPA = eosinophilic granulomatosis with polyangiitis; MPO-ANCA = myeloperoxidase antineutrophil cytoplasmic antibody; TB = tuberculosis." (PMID 41480456, 2025). "Based on the biopsy and a positive anti-myeloperoxidase antibody (anti-MPO/p-ANCA) result, a diagnosis of eosinophilic granulomatosis with polyangiitis (EGPA) was made." (PMID 37941858, 2023). "With additional elevated anti-MPO-ANCA and elevated Troponin T, the patient was admitted to the ICU and diagnosed with eosinophilic granulomatosis with polyangiitis (EGPA)." (PMID 37234094, 2023).
systemic vasculitis (49 papers, 2012 to 2025). "In this study we define the role of ecDNA in systemic vasculitis affecting the kidney, using human kidney biopsies and murine models of myeloperoxidase anti-neutrophil cytoplasmic antibody-associated glomerulonephritis (MPO-ANCA GN)." (PMID 40632882, 2025). "Transfer of splenocytes from MPO-deficient mice immunized with mouse MPO into wild-type mice resulted in hyperimmune systemic vasculitis." (PMID 36119110, 2022). "MPA is a systemic vasculitis of small-to-medium-sized vessels that is associated with antibodies directed against the target antigen MPO." (PMID 33281701, 2020). "The use of propylthiouracil (PTU) is associated with the development of autoantibodies, namely, antineutrophil cytoplasmic antibodies (ANCAs), which are associated with the pathogenesis of ANCA-associated systemic vasculitis, most often related to the myeloperoxidase subtype (ANCA-MPO)." (PMID 36000132, 2022). "Antineutrophil cytoplasmic antibody (ANCA)-associated vasculitis (AAV) is characterized by necrotizing vasculitis, predominantly affecting small vessels associated with myeloperoxidase (MPO)-ANCA or proteinase 3 (PR3)-ANCA according to the Chapel Hill Consensus Conference." (PMID 29262790, 2017). "The contrary scenario was also observed, in which a patient with fibrosing ILD and positive MPO‐ANCA antibody serology at diagnosis subsequently evolved into overt systemic vasculitis." (PMID 36284753, 2022). "In systemic vasculitis, the intracellular target autoantigens are proteinase-3 (PR3) and myeloperoxidase (MPO), which have signal peptides that allow their association with and storage in secretory vesicles." (PMID 33763057, 2021). "Here, we have investigated the effect of SYK inhibition in an experimental model of myeloperoxidase (MPO)-ANCA–induced systemic vasculitis (experimental autoimmune vasculitis [EAV]) that was developed in our laboratory." (PMID 32305129, 2020). "These cases were diagnosed as PAN because the pathological findings showed necrotizing vasculitis in small and medium-sized arteries despite being MPO-ANCA-positive." (PMID 30850017, 2019). "Her serology was found to be positive for antinuclear antibodies and myeloperoxidase antibodies, resulting in a renal biopsy, which revealed an acute necrotizing vasculitis consistent with AAV." (PMID 30083557, 2018). "GPA is identified by the presence of granulomas and serine proteinase-3 positivity, while MPA is marked by necrotizing vasculitis without granulomas and is associated with myeloperoxidase (MPO) positivity." (PMID 39949870, 2025). "Because ANCA vasculitis and IBD can co-occur in rare circumstances, the presence of myeloperoxidase (MPO) or p-ANCA antibodies in IBD patients may prompt numerous studies aimed at ruling out systemic vasculitis." (PMID 38725759, 2024). "Antineutrophil cytoplasmic antibody (ANCA)-associated vasculitides (AAV) are a group of systemic vasculitis characterized by autoantibodies against neutrophil cytoplasmic antigens (proteinase 3 PR3-ANCA and myeloperoxidase MPO-ANCA) and inflammation of small vessels." (PMID 36104505, 2023). "Additionally, the levels of anti-myeloperoxidase (anti-MPO) and anti-proteinase 3 (anti-PR3) antibodies are useful to diagnose antineutrophil cytoplasmic antibodies associated with systemic vasculitis and related kidney damage." (PMID 30013843, 2018). "Moreover, an interaction between Cp and myeloperoxidase (MPO) was also demonstrated and it is supposed that Cp inhibits prooxidant activity of MPO; in fact, in systemic vasculitis, the interaction between Cp and MPO is prevented by autoantibodies against MPO." (PMID 28118841, 2017). "Antineutrophil cytoplasmic antibody (ANCA)-associated vasculitides (AAV) are a group of systemic vasculitis characterized by inflammation of small vessels and in most of the cases presence of autoantibodies against neutrophil cytoplasmic antigens (proteinase 3 PR3-ANCA and myeloperoxidase MPO-ANCA)." (PMID 36104505, 2023).
systemic vasculitis (continued). "The first one is the neutrophil pathway: ANCA bind to membrane-bound myeloperoxidase (MPO) and proteinase-3 (PR-3) molecules of neutrophils, causing them to adhere to the endothelial wall of small vessels and degranulate, resulting mainly in the necrotizing vasculitis component of the disease." (PMID 33817427, 2021). "The patient exhibited characteristic features of AAV, including positive P-ANCA and elevated myeloperoxidase (MPO)-ANCA titers, confirmed by biopsy showing multifocal necrotizing vasculitis and chronic-active interstitial nephritis." (PMID 40932947, 2025). "Two principal antigens on neutrophils—namely, proteinase 3 (PR3) and myeloperoxidase (MPO)—provide epitopes for ANCA binding, promoting endothelial damage and vascular inflammation, culminating in necrotizing vasculitis." (PMID 36834488, 2023). "Direct evidence for ANCA pathogenicity comes from an animal model in which the passive transfer of MPO-ANCA resulted in pauci-immune crescentic GN and necrotizing vasculitis in small vessels." (PMID 32085664, 2020). "In patients with (primary) systemic vasculitis, ANCA antibodies are usually directed against proteinase 3 (PR3) or myeloperoxidase (MPO)." (PMID 33282799, 2020). "This problematic matter has influenced the treatment strategy of MPO-ANCA-positive ILD patients without systemic vasculitis." (PMID 35807120, 2022). "In our series, a number of additional patients with fibrosing ILD and positive MPO‐ANCA serology without evidence of systemic vasculitis remain under close observation." (PMID 36284753, 2022). "Needless to say, this problematic matter has influenced the treatment strategy of MPO-ANCA-positive ILD patients without systemic vasculitis as a form of idiopathic ILD." (PMID 35807120, 2022). "MPO-ANCA-positive ILD without systemic vasculitis (i.e., idiopathic ILD) also showed a similar tendency (UIP: 12.9–53.9%, non-UIP: 13.6–58.1%)." (PMID 35807120, 2022). "Finally, as occurs in systemic vasculitis, activated neutrophils release EV expressing the myeloperoxidase (MPO) which by activating the myeloperoxidase-hydrogen peroxide-chloride system, leads to endothelial damage." (PMID 33919576, 2021). "One of 229 patients was positive for myeloperoxidase antineutrophil cytoplasmic antibody with laryngeal chondritis and had no signs of systemic vasculitis." (PMID 32944685, 2020). "Anti-neutrophil cytoplasmic antibody (ANCA)-associated vasculitis (AAV) is a rare necrotizing vasculitis with few or no immune deposits, predominantly affecting small vessels associated with ANCA specific for myeloperoxidase (MPO) or proteinase 3 (PR3)." (PMID 30328500, 2018). "The pathological and physiological roles of ANCA to minor antigens, other than PR3 and MPO, have not been determined, but some cases have been reported in relation to systemic vasculitis." (PMID 25648906, 2015). "On clinical follow-up at sixteen months, the patient had not displayed evidence of systemic vasculitis despite remaining persistently anti-MPO antibody positive." (PMID 26558120, 2015). "However, given the muscle involvement of systemic vasculitis, we suggest that even when patients can be classified as having PM/DM, the 2022 ACR/EULAR criteria for MPA should be applied simultaneously to patients with MPO-ANCA (or P-ANCA) and ILD." (PMID 37959218, 2023). "Initially, when MPO-ANCA-positive ILD without systemic vasculitis is considered, clinicians should determine whether the patient has a UIP pattern on HRCT." (PMID 35807120, 2022). "In MPO-ANCA-positive ILD without systemic vasculitis as a form of idiopathic ILD, whether there is a difference in survival time and prognosis between patients with MPA-ILD and those with idiopathic ILD is currently controversial." (PMID 35807120, 2022).